DCK (deoxycytidine kinase)
Description:
Phosphorylates the deoxyribonucleosides deoxycytidine, deoxyguanosine and deoxyadenosine. Has broad substrate specificity, and does not display selectivity based on the chirality of the substrate. It is also an essential enzyme for the phosphorylation of numerous nucleoside analogs widely employed as antiviral and chemotherapeutic agents.
Tractability: Small molecule: a structure with a bound ligand is known; a high-quality ligand is known; it has a high-quality binding pocket; it belongs to a druggable protein family. PROTAC: ubiquitination databases record sites on it; its protein half-life has been measured; a small molecule that binds it is known.
Target class: Enzyme; Transferase
Safety:
Unwanted effects reported when the protein is acted on. In parentheses: how it was acted on, where the effect was seen, and who reports it.
neutropenia (source: ClinPGx)
Gene: Protein-coding gene on chromosome 4 (70,992,538 to 71,030,914, forward strand). Ensembl gene ENSG00000156136.
Subcellular location: Nucleus
Subcellular location (Human Protein Atlas): Nucleoplasm
Pathways (Reactome):
Metabolism: Purine salvage; Pyrimidine salvage
Gene Ontology:
Molecular function: cytidine kinase activity; deoxyadenosine kinase activity; deoxycytidine kinase activity; deoxyguanosine kinase activity; protein binding; protein homodimerization activity; ATP binding; deoxynucleoside kinase activity
Biological process: nucleoside phosphate biosynthetic process; pyrimidine nucleotide metabolic process; carbohydrate derivative metabolic process; CMP biosynthetic process; dAMP biosynthetic process; deoxyribonucleoside monophosphate biosynthetic process; purine nucleotide salvage
Cellular component: nucleoplasm; cytoplasm; cytosol; mitochondrion; nucleus
Genetic constraint (gnomAD): Loss-of-function variants: 11 observed, 17.66 expected, observed/expected ratio (o/e) 0.62, 90% interval 0.39 to 1.03. The upper end of that interval is the gene's LOEUF score, 1.03, which puts it in group 4 of 6, group 1 being the genes least tolerant of losing a copy. Missense variants: 144 observed, 164.46 expected, observed/expected ratio (o/e) 0.88, 90% interval 0.76 to 1. Synonymous variants: 58 observed, 56.63 expected, observed/expected ratio (o/e) 1.02, 90% interval 0.83 to 1.27.
Homologues: Orthologues: chimpanzee DCK (97% identical), mouse Dck (93% identical), rat Dck (92% identical), guinea pig DCK (91% identical), macaque DCK (91% identical), dog DCK (87% identical), tropical clawed frog dck (81% identical), rabbit DCK (79% identical), zebrafish dck (71% identical). Paralogues in human: DGUOK (47% identical), TK2 (32% identical), NDUFA10 (23% identical).
Diseases named in the same sentence as DCK in open-access papers:
DCK is named in the same sentence as 69 diseases in open-access papers, as found by Europe PMC text mining. Sharing a sentence is not in itself a finding about the gene and the disease. The quoted sentences say what the papers report.
pancreatic cancer (51 papers, 2005 to 2025). "Studies have shown that a low expression of dCK has been linked to poor prognoses and reduced survival rates in resectable pancreatic cancer patients receiving gemcitabine therapy." (PMID 38275398, 2024). "More specifically, in pancreatic cancer cells, deoxycytidine kinase (dCK) mRNA interacts with HuR encoding the enzyme that metabolizes and activates gemcitabine." (PMID 34572861, 2021). "For instance, high expression of hENT1 and dCK mRNA in resected specimens from patients with pancreatic cancer is associated with long overall survival, disease-free survival and disease progression." (PMID 34237099, 2021). "The expression of the dCK gene and protein and single-nucleotide SNPs in the dCK gene have been closely associated with gemcitabine chemosensitivity in patients with pancreatic cancer." (PMID 29113399, 2017). "An abundance of dCK is commonly known to be associated with gemcitabine sensitivity in pancreatic cancer." (PMID 23710668, 2013). "Conversely, pancreatic cancer cells overexpressing HuR are more sensitive to gemcitabine compared to control cells due to a stabilization of the deoxycytidine kinase (dCK) mRNA, encoding the enzyme that metabolizes and thereby activates gemcitabine." (PMID 22436134, 2012). "Moreover, it has also been reported that deficiency of dCK enhances resistance to acquired gemcitabine, and transfection with hCNT3 greatly increases gemcitabine uptake to overcome resistance in pancreatic cancer." (PMID 34237099, 2021). "Interestingly, both RRM2 and DCK are reported to be associated with the drug sensitivity of gemcitabine (a common chemotherapeutic drug for pancreatic cancer and many other types of cancer)." (PMID 33520699, 2020). "As the KBM7 cells are of leukaemic origin and near-haploid genotype, representing a very specific cancer entity, we next validated whether DCK inactivation also causes resistance to gemcitabine and entinostat in pancreatic cancer cells." (PMID 28969017, 2017). "On the other hand, the protein was not expressed in Messa 10K (human ovarian sarcoma), CHO dCK- (chinese hamster ovary dCK deficient cell line) and MiaPaCa2 (pancreatic cancer cell line), three cell lines which are known to be resistant to gemcitabine treatment." (PMID 29127277, 2017). "In this study, we established various gemcitabine-resistant subclones of human pancreatic cancer cell lines, and investigated changes in gene expression associated with gemcitabine transport and metabolism, that is, hENT1, dCK, RRM1, and RRM2 mRNA, in the development of gemcitabine resistance." (PMID 17224927, 2007). "Recent findings suggest that dCK polymorphisms, such as the CC genotype of rs1044457, might influence dCK expression and, ultimately, gemcitabine activity in various cancers, including pancreatic cancer." (PMID 40657553, 2025). "Other miR-155 targets associated with chemoresistance include the gemcitabine-metabolizing enzyme deoxycytidine kinase (DCK) in pancreatic cancer and tumor necrosis factor-α-inducible protein 8 (TNFAIP8) in bortezomib-resistant multiple myeloma cells." (PMID 41463125, 2025). "Clinical studies have shown that dCK gene polymorphism (such as rs11158728 SNP) can reduce the enzyme, and the objective response rate (ORR) of pancreatic cancer patients with low activity genotype decreases." (PMID 41293424, 2025). "We also explored the reasons for the increased sensitivity ofNCOA6 knockdown to gemcitabine from the perspective of the mechanism of gemcitabine resistance.hENT,dCK andRRM1 are genes related to drug resistance in pancreatic cancer." (PMID 40065720, 2025). "The knockout of DCK or CCNL1 by the CRISPR/Cas9 system promotes gemcitabine resistance in pancreatic cancer cells." (PMID 35804923, 2022). "Appropriately, HuR’s overexpression leads to dCK mRNA increase in pancreatic cancer cells, while its silencing reduces dCK levels." (PMID 34572861, 2021).
pancreatic cancer (continued). "The deoxycytidine kinase reduction by miR-155 delivered by the extracellular vesicles led to abrogation of acquired resistance of gemcitabine in pancreatic cancer cells." (PMID 34683931, 2021). "Two less studied predictive markers of pancreatic cancer are deoxycytidine kinase (DKC) and human equilibrative nucleoside transporter (hENT1), which have both been found to be overexpressed in the disease." (PMID 32380649, 2020). "Clinical studies have shown that the DCK expression level in pancreatic cancer tissue is a reliable prognostic indicator of PFS, suggesting that DCK is a good biomarker of gemcitabine sensitivity for pancreatic cancer patients treated with gemcitabine." (PMID 35582220, 2020). "DCK has a negative regulatory effect on the proliferation and metastasis of pancreatic cancer cells." (PMID 32920549, 2020). "Currently, the solution to gemcitabine resistance in pancreatic cancer is to bypass the NTs and dCK through different mechanisms or drug modifications, thereby enhancing the transport and phosphorylation of gemcitabine." (PMID 31514451, 2019). "By overexpressing dCK in pancreatic cancer cells, we assessed the impact of dCK on NRF2 transcriptional activity." (PMID 29701272, 2018). "In pancreatic cancer, dCK catalyses gemcitabine activation, and decreased dCK expression is considered an important factor governing gemcitabine resistance." (PMID 29701272, 2018). "Decreased deoxycytidine kinase (dCK) expression is a reported indicator of gemcitabine efficacy in pancreatic cancer, due to the impact of this kinase on gemcitabine metabolism." (PMID 29701272, 2018). "In the end, dCK has been demonstrated in vitro to possess tumour suppressive roles in pancreatic cancer cell lines." (PMID 29701272, 2018). "Decreased dCK expression has been reported to participate in gemcitabine resistance in pancreatic cancer, which is correlated with NRF2/ARE activation." (PMID 29701272, 2018). "By employing immunohistochemistry, a small retrospective study found that high levels of dCK protein expression correlated positively with OS in pancreatic cancer patients undergoing adjuvant gemcitabine chemotherapy." (PMID 29113399, 2017). "Our recent findings indicate that miR-155 induces chemoresistance in pancreatic cancer cells via inhibiting deoxycytidine kinase (DCK) expression." (PMID 28383487, 2017). "Although DCK was expressed in all the pancreatic cancer cell lines examined, its expression level did not correlate with the cell line sensitivity to gemcitabine and entinostat." (PMID 28969017, 2017). "CRISPR/Cas-9 inactivation of DCK in pancreatic cancer cell lines resulted in resistance to gemcitabine alone and in combination with entinostat." (PMID 28969017, 2017). "Upon exposure to gemcitabine, HuR translocates from the nucleus to a cytoplasmic localization in pancreatic cancer cells and, through its dCK regulating activity, sensitizes the cells to gemcitabine." (PMID 29144412, 2017). "Immunohistochemically, low expression of dCK correlated with both reduced OS and old patient age, suggesting age-related epigenetic regulation of the dCK gene in pancreatic cancer patients." (PMID 29144412, 2017). "An analysis of pancreatic cancer patients treated with gemcitabine found that DCK levels correlated with prolonged survival, but little else has been reported linking DCK to cancer." (PMID 29018771, 2017). "In pancreatic cancer, high dCK expression was identified as an independent prognostic factor in patients who received adjuvant gemcitabine therapy." (PMID 23710668, 2013). "As an example, SLC29A1 and DCK silencing via DNA methylation in some gemcitabine-resistant pancreatic cancer patients could be targeted with a pharmaco-epigenetic approach using DNMT inhibitors alongside gemcitabine." (PMID 40723396, 2025).
pancreatic cancer (continued). "A phase II clinical trial (NCT03247088) demonstrated that in advanced pancreatic cancer patients with low dCK expression, the decitabine combination regimen achieved an objective response rate (ORR) of 34%, significantly higher than the 12% observed in the gemcitabine monotherapy group (p = 0.013)." (PMID 41293424, 2025). "Hence, characterizing DCK-inactivated and downregulated cells is crucial for the improvement of pancreatic cancer treatment outcomes." (PMID 38346958, 2024). "Additionally, exosomes with miR-155 have also been closely implicated in GEM metabolism and inactivation, via suppressing the GEM-metabolizing enzyme DCK in pancreatic cancer cells." (PMID 38542378, 2024). "Gemcitabine treated pancreatic cancer cells can enrich dCK mRNA and improve cytoplasmic HuR levels." (PMID 31514451, 2019). "Therefore, the overexpression of HuR will increase, and the silence of HuR will reduce the expression of dCK protein, thus producing the corresponding gemcitabine response in pancreatic cancer." (PMID 31514451, 2019). "Together with previous dCK reports, we have increased the understanding of the role of this enzyme in pancreatic cancer and have shed light on novel strategies for improving chemotherapy resistance in pancreatic cancer." (PMID 29701272, 2018). "Uncovering the signalling pathways affected by dCK might provide novel strategies for improving chemotherapy and radiotherapy in pancreatic cancer." (PMID 29701272, 2018). "Similar to the related nucleoside analog termed cytarabine (Ara-C), GEM is taken up within pancreatic cancer cells through equilibrative nucleoside transporter-1 (hENT1), and subjected to deoxycytidine kinase (dCK)-mediated phosphorylation to become an active form (dFdCTP)." (PMID 29558908, 2018). "As observed above, dCK regulates the Keap1/NRF2/ARE axis in pancreatic cancer cells." (PMID 29701272, 2018). "On the basis of our observations of the negative correlation between dCK and NRF2 expression and the decisive roles of NRF2 in pancreatic cancer oncogenesis and progression, we proposed that dCK might inhibit pancreatic cancer cell proliferation." (PMID 29701272, 2018). "We show that DCK is a critical determinant of sensitivity to treatment with gemcitabine alone or in combination with entinostat in pancreatic cancer cells, demonstrating the ability of this system to reveal the critical mediators of response to cancer therapeutics." (PMID 28969017, 2017). "dCK protein expression positively correlates with HuR protein levels and efficacy of gemcitabine, accordingly overexpression of HuR elevates, while silencing of HuR reduces dCK protein expression, conferring corresponding gemcitabine responses in pancreatic cancer cells." (PMID 29144412, 2017). "Deoxycytidine kinase is the main rate-limiting enzyme of intracellular activation and metabolism of gemcitabine, and its expression generally corresponds to the degree of gemcitabine resistance in pancreatic cancer patients." (PMID 29144412, 2017). "To investigate the effect of the insertion of G12 in tumour cells that express an endogenous functional dCK protein, we assessed the phenotype conferred by the insertion of the mutated dCK to the colon carcinoma cell line HT29, and to the pancreatic cancer cell line BxPC3." (PMID 22927829, 2012). "Consequently, DCK is associated with prolonged survival of patients after adjuvant gemcitabine therapy for resected pancreatic ductal adenocarcinoma (PDAC), and downregulation of DCK in vitro enhances resistance against gemcitabine in pancreatic tumor cells." (PMID 24212609, 2010). "dCK mRNA expression is a candidate indicator for GEM efficacy in unresectable pancreatic cancer." (PMID 19531250, 2009). "In conclusion, dCK mRNA expression in EUS-FNA biopsy specimens may be a predictor for response to GEM in patients with unresectable pancreatic cancer." (PMID 19531250, 2009).
pancreatic cancer (continued). "Thus, both the simultaneous significant increase in the expression of the activating enzyme (dCK) and the decrease of the deactivating one (5′-NT) suggested a possible role of fluvastatin in the activating metabolism of gemcitabine in pancreatic cancer cells." (PMID 16052215, 2005). "Therefore, monitoring the expression of dCK could be crucial for predicting the responses of pancreatic cancer patients to gemcitabine therapy." (PMID 38275398, 2024). "However, the impact of dCK on pancreatic cancer proliferation and the related signalling pathways that might be involved in gemcitabine have seldom been reported." (PMID 29701272, 2018). "However, the regulatory mechanisms of dCK have seldom been discussed in pancreatic cancer." (PMID 29701272, 2018). "Western blot analysis and qRT-PCR results confirmed that the expressions of hENT and dCK were upregulated and that the expression of RRM1 was downregulated in pancreatic cancer cells withNCOA6 knockdown." (PMID 40065720, 2025). "For instance, research in pancreatic cancer demonstrates that the coadministration of HDAC inhibitors and gemcitabine enhances SLC29A1 and DCK gene expression, which are integral to gemcitabine transport and activation." (PMID 40723396, 2025). "First, we evaluated the expression of NT5C1A, CDA and DCK in KPC mice and OTM by analyzing the expression of GME in bulk pancreatic cancer tissue." (PMID 38744194, 2024). "We performed genome-wide CRISPR/Cas9 knockout screening in the mouse pancreatic cancer cell line TB32047 with gemcitabine treatment and identified deoxycytidine kinase (DCK) and cyclin L1 (CCNL1) as the top hits." (PMID 35804923, 2022). "We demonstrated that DCK and CCNL1 contribute to gemcitabine resistance in pancreatic cancer by performing genome-wide CRISPR/Cas9 knockout screening in the mouse pancreatic cancer cell line TB32047 under gemcitabine treatment." (PMID 35804923, 2022). "We found that DCK was decreased and CDA was overexpressed in gemcitabine resistant tumor samples and pancreatic cancer cells." (PMID 34458141, 2021). "Numerous studies have indicated that hENT1, dCK and RRM1 are key proteins for gemcitabine resistance in pancreatic cancer." (PMID 30867652, 2019). "The expression of the main four factors (hENT1, dCK, RRM1 and RRM2) involved in gemcitabine transport and metabolism was also shown to correlate with acquired resistance to gemcitabine in pancreatic cancer cells." (PMID 31652737, 2019). "Using the CRISPR/Cas9 gene editing system, we inactivated DCK in PANC-1 and SUIT2 pancreatic cancer cells." (PMID 28969017, 2017). "Regarding Gem, reduced phosphorylation by dCK was identified to be a key process for acquiring Gem resistance over other processes via ENT1 and CDA in a pancreatic cancer cell line." (PMID 26622566, 2015). "Marechal and colleagues recently investigated the predictive value of hENT1, dCK, and RRM1 in patients with pancreatic cancer treated with adjuvant gemcitabine chemotherapy and demonstrated that both hENT1 and dCK expressions were powerful predictive markers." (PMID 23710668, 2013). "This analysis revealed an increase of CDA (P=0.003), DCK (P=0.06), DPYD (P=ns) and TP (P=0.01) in pancreatic cancer tissues, whereas hENT1 (P=ns) expression was slightly reduced compared with the normal pancreas." (PMID 18728667, 2008). "In this study, we applied genome-wide CRISPR/Cas9 loss-of-function screening with gemcitabine treatment to identify DCK and CCNL1 as genes that contribute to gemcitabine resistance in pancreatic cancer and explored the mechanism of CCNL1-related gemcitabine resistance." (PMID 35804923, 2022). "DCK was expressed in 55 out of 60 pancreatic cancer cores, in the cytoplasm and strongly in the nucleus, not only in tumour cells, but also in stromal and immune cells in the tumour microenvironment." (PMID 31113993, 2019).